RIPK3 (receptor interacting serine/threonine kinase 3)
Diseases named in the same sentence as RIPK3 in open-access papers (continued):
Sharing a sentence is not in itself a finding about the gene and the disease.
viral infection (58 papers, 2015 to 2025). "Similar outcomes have been observed in viral infection models, where RIPK3-deficient hosts exhibit elevated viral loads and worsened neuroinflammation, as seen in herpes simplex virus type 1 (HSV-1) infection." (PMID 41142308, 2025). "Our results confirm that RIPK3 is implicated in a protective response during viral infection but only at a limited range of IAV challenge doses." (PMID 33976111, 2021). "Thus, it is commonly assumed that once ZBP1 binds Z-form nucleic acid ligands during viral infection, it directly associates with and activates RIPK3." (PMID 39345610, 2024). "Interestingly, another cell death program, termed necroptosis, has been also implicated in control of viral infection via receptor-interacting serine/threonine protein kinase 3 (RIPK3)." (PMID 28410401, 2017). "One example is RIPK3 (receptor-interacting serine/threonine protein kinases 3), which contributes to necroptosis during inflammation, including during viral infection." (PMID 41345807, 2025). "ZBP1 is known to initiate RIPK3-mediated necroptosis in murine models of viral infection, but how this pathway is regulated in human cells is unclear." (PMID 39982916, 2025). "ZBP1 can sense viral infections and activate RIPK3, thus inducing RIPK1-independent activation of necroptosis." (PMID 40261527, 2025). "Nec-1 treatment can mitigate the HL caused by cisplatin and kanamycin, can protect HCs from damage by cisplatin, TM, and virus infections, and can protect SGNs from damage by ouabain and RIPK3 overexpression." (PMID 40261527, 2025). "Ponatinib, which is reported to directly target and inhibit RIPK1 and RIPK3, can protect HCs from damage by viral infections." (PMID 40261527, 2025). "Recently, ZBP1 has been shown to recognize Z-RNA as the ligand to trigger RIPK3-mediated necroptosis during virus infection." (PMID 39345610, 2024). "It was further found that the CSFV NS4A protein interacts with the E3 ubiquitin ligase TRIM25 and is targeted to mediate the autophagic degradation of RIPK3, thereby blocking the progression of necroptosis to achieve persistent viral infection." (PMID 38100396, 2024). "PRV VP22 disrupts the binding between ZBP1 and RIPK3/Caspase-8 and inhibits the cleavage of Caspase-1 and IL-1β induction, thereby promoting viral infection." (PMID 39475237, 2024). "OASL chaperones the assembly of RIPK3 and ZBP1 via liquid-liquid phase separation, which induces RIPK3 and necroptosis activation, thereby modulating inflammation and host defence against viral infection." (PMID 36604592, 2023). "This explains why Zα-deficient ZBP1 can still mediate heat stress-induced RIPK3 activation and PCD despite being completely inactivated by viral infection." (PMID 36849530, 2023). "It is evident in the literature that the majority of the studies, looking at the role of necroptosis in viral infection, have focused on RIPK3 and its activation." (PMID 36175538, 2023). "ZBP1 is one of the cytoplasmic sensors that regulate cell death and inflammation and initiates the RHIM-dependent activation of RIPK3-dependent necroptosis during virus infections." (PMID 35215199, 2022). "Of note, necroptosis can be elicited in a RIPK1-independent way, using Toll-like receptors (TLR) 3 and 4, or viral infections via acid nucleic sensors recruiting the RIPK3-MLKL axis." (PMID 36613804, 2022). "Our results reveal that even a low viral infection dose is sufficient to kill all Ripk3−/−Fadd−/− DKO mice shortly after infection even to a higher extend than Ripk3−/− mice, showing indicating that FADD-mediated apoptosis is implicated." (PMID 33976111, 2021). "Recently, a number of studies found that RIPK3 mediated complicated roles in cell death, inflammation, and immune defense during virus infection depending on different host cells and viruses." (PMID 32265853, 2020).
viral infection (continued). "Previous reports describing ZBP1 induction of apoptosis in response to viral infection have indicated that, depending on cellular conditions, cell death can proceed in both a RIPK3-dependent and RIPK3-independent manner." (PMID 32649716, 2020). "RIPK3 participated in the regulation of inflammation and cell survival, which directly or indirectly affected the propagation of virus during virus infection." (PMID 32265853, 2020). "In summary, RIPK3 has complicated roles in neuroinflammation and virus propagation during viral infection." (PMID 32265853, 2020). "Viral infections have been reported to simultaneously trigger necroptosis and RIPK3/caspase-8 mediated apoptosis within mammalian fibroblasts and lung epithelial cells." (PMID 29643440, 2018). "Mechanistic studies revealed that CSFV NS4A protein promoted tripartite motif-containing 25 expression, synergistically induced the occurrence of mitophagy, targeted the autophagic degradation of RIPK3 to block the progression of necroptosis occurrence, and achieved persistent viral infection." (PMID 38100396, 2024). "Both the in vitro phase-separation assays and the virus infection study collectively show that OASL drives the condensation of RIPK3 and ZBP1 by recruiting them into its liquid droplets via protein–protein interactions, which ultimately induces RIPK3 autophosphorylation." (PMID 36604592, 2023). "Involvement of MLKL in viral infection/response can be divided into two categories: RIPK3 mediated activation of MLKL (Vaccinia virus, Cytomegalovirus, Influenza virus) and MLKL direct targeting (BeAn 58058 poxivirus (BAV), Cotia Poxvirus (COTV) and human HCMV UL36)." (PMID 36175538, 2023). "Given the differential transcriptional upregulation of MLKL and RIPK3, one could hypothesise that these two molecules might also have alternative roles in the response to viral infection or inflammation, independent from each other." (PMID 36175538, 2023). "Lastly, viral infection elicits the production of TNF that can act in an autocrine/paracrine manner to initiate apoptosis in the presence of functional caspase-8, or necroptosis via the association of RIPK1 with RIPK3 in its absence." (PMID 35549723, 2022). "If the caspase system is compromised by pharmacology or by a viral infection, cells expressing RIPK3 can initiate necroptosis by the formation of a RIPK1-RIPK3 complex named “necrosome”, via their RIP homotypic interaction motives, and forming an amyloidal protein complex." (PMID 36613804, 2022). "ZBP1 is known to interact with RIPK3 to mediate viral infection-induced necroptosis." (PMID 33976222, 2021). "Thus, HSV1 ICP6 RHIM mutant virus infection promotes the rapid assembly of a ZBP1-RIPK3-MLKL necrosome-like complex that drives RIPK3-dependent phosphorylation of MLKL and subsequent death of virus-infected cells." (PMID 30050136, 2018). "Interestingly, the receptor interacting serine/threonine protein kinase (RIPK) family members (RIPK1 and RIPK3) regulate necroptosis (a form of programmed necrosis) and play a critical role in immunity to viral infections." (PMID 28410401, 2017). "Unlike TLR3–IFN deficiency, which has also been reported in patients with severe viral diseases of tissues other than the brain, such as severe influenza and COVID-19 pneumonia, deficiencies of snoRNA31, RIPK3 and DBR1 have not yet been detected in patients with viral infections of other organs." (PMID 39048830, 2024). "Moreover, the increased expression of necrosis‐related proteins (p‐MLKL, RIPK1, and RIPK3) induced by viral infection was reduced by pyrogallol, suggesting that pyrogallol could alleviate H1N1 virus‐triggered necrosis." (PMID 38617435, 2024). "Interestingly, it has been suggested that the enhanced susceptibility of Ripk3−/− mice to WNV is due to an abolition of neuronal chemokine expression, leading to lower levels of T-lymphocyte and myeloid-cell recruitment to the CNS to restrict viral infection." (PMID 37083451, 2023).
viral infection (continued). "Hence, unrestrained activation of RIPK3 will be detrimental to the host during virus infection." (PMID 36016369, 2022). "A protective role of Receptor Interacting Serine/Threonine Kinase 3 (RIPK3) has been reported against viral infections including influenza A virus and RIPK3 is known as a key factor upon viral infection that determines whether the infected cells undergo apoptosis or necroptosis." (PMID 30356848, 2018). "Under virus infection, which promotes Ripk1-dependent necrosis by stimulating tumor necrosis factor (TNF), Ripk3 subsequently induced the phosphorylation of Ripk1, which resulted in the formation of a pro-necrotic necrosome complex." (PMID 36849513, 2023). "Expression of OASL1–mCherry effectively sequestered both RIPK3 and ZBP1 into its condensate in the cytoplasm during virus infection." (PMID 36604592, 2023). "If it is found that pathogenic CoVs do indeed produce Z-RNA (as the ZH3 algorithm predicts) and that the RHIM in Nsp13 regulates ZBP1, RIPK3, RIPK1, TRIF or SMG1 signaling, then we suggest that effects will depend on the stage of viral infection." (PMID 35784331, 2022). "Although Zbp1 has not yet been studied as an atherosclerosis modifier, it has a role as a sensor of viral infections, in NLRP3 regulation after viral infection, and a role in necroptosis and inflammation via its effects on the RIPK1, RIPK3, and MLKL pathways." (PMID 35052410, 2021). "It has been shown that RIPK3/MLKL-mediated necroptosis has antiviral function in fibroblast and epithelial cells during lytic virus infection by destroying viral reservoirs." (PMID 32265853, 2020). "Following viral infection or the ligation of pattern recognition receptors, ZBP1 and TRIF interact with RIPK3 through their RHIM domains to initiate the necroptotic process." (PMID 31922095, 2019). "This indicates that another kinase-independent trigger of RIPK3 induced cell death, as viral infection lead to FADD-dependent, but RIPK3-independent apoptosis." (PMID 31766571, 2019). "Receptor-interacting serine/threonine-protein kinase-3 (RIPK3), a central player of necroptosis, has been shown to play an additional role during virus infection." (PMID 30261081, 2018). "Although these RIPK1- and RIPK3-targeting inhibitors have yet to be evaluated in the context of PED, and no experimental data are currently available, prior studies in other viral infections highlight their potential translational value as candidate strategies for PED management." (PMID 41295687, 2025). "In addition, RIPK3 inhibitors such as GSK’872, GSK’843, GSK’840, and UH15-38 have exhibited efficacy in multiple viral infection models." (PMID 41295687, 2025). "The RIPK3-MLKL pathway, which includes receptor-interacting serine/threonine-protein kinase 3 (RIPK3) and mixed lineage kinase domain-like pseudokinase (MLKL), is essential for regulating necroptosis, especially in response to viral infections or cellular stress." (PMID 39735183, 2024). "Therefore, we examined the interactions between RIPK3 and ZBP1 or Caspase-8 during viral infections." (PMID 39475237, 2024). "Maybe this is an indication of other unknown functions of MLKL in viral infection which are yet to be discovered, or maybe the ability of MLKL to feed back into other modalities of cell death similarly to RIPK3 in the case of influenza infection." (PMID 36175538, 2023). "Collectively, the markedly reduced activation of the key necroptotic kinase RIPK3 and the effector MLKL upon virus infection in Oasl1–/– mice suggests that OASL1 has a pivotal role in the execution of necroptosis in vivo to restrict MCMV replication and elicit antiviral inflammatory responses." (PMID 36604592, 2023). "Receptor interacting serine/threonine-protein kinase 3 (RIPK3) has been shown to participate in several biological or pathological processes and play complicated and even controversial roles in different host cells during various viral infections." (PMID 32265853, 2020).
viral infection (continued). "For viral infection-induced necroptosis, RIPK3 and MLKL, but not RIPK1, are required and another protein, Z-DNA-binding protein 1 (ZBP1), also known as DNA-dependent activator of IFN regulatory factors (DAI), functions upstream of RIPK3-MLKL to initiate the formation of the necrosome." (PMID 36703228, 2023). "Additionally, animal data suggests the RIPK3 RHIM is a potent driver of septic inflammation independent of its cell death function, and loss of RIPK3, but not MLKL, improves control of viral infection." (PMID 38274794, 2023). "Our model suggests that the OASL–RIPK3 interaction enhances the formation of the RIPK3 amyloid-like fibril signalling complex, which prolongs RIPK3 activation and drives high levels of MLKL phosphorylation, ultimately inducing robust necroptosis during virus infection." (PMID 36604592, 2023). "Furthermore, the effect of RIPK3 and MLKL knockdown on cell death demonstrated their essential roles in virus-induced necroptosis, although the transcription levels of RIPK3 and MLKL were downregulated by virus infection." (PMID 34149651, 2021). "Even following viral infections with influenza or SARS-CoV-2, proinflammatory cytokines such as TNF and IFN-γ can also induce necroptosis or PANoptosis via other caspases and kinases such as the Receptor-Interacting Serine/Threonine Kinase 3 (RIPK3) and Casp-8." (PMID 34571869, 2021). "Indeed, consistent with the cell viability assay, RIPK1 co-immunoprecipitated with ZBP1 and RIPK3 in necroptosis-susceptible cells (HT29 WT, mutZα1, and mutRHIMB) following viral infection but was not in cells with inactivating mutations in Zα2 or RHIM A (mutZα2, mutZα1Zα2, and mutRHIMA)." (PMID 39345610, 2024). "Furthermore, animals lacking RIPK3 are more vulnerable to certain types of viral infection." (PMID 36849530, 2023). "Using an inhibitor of RIPK1 to pre-treat cells, necroptosis was not affected after viral infection indicating that the ZIKV-induced necroptosis was not RIPK1 dependent and neither RIPK3 nor necrosome was probably not activated by RIPK1 in astrocytes." (PMID 33796483, 2021). "Recent studies have reported that RIPK1 kinase activity is not universally required for all necroptosis instances, as RIPK3 can be activated independently of RIPK1 by external stimuli, such as viral infection, heatstroke, and osmotic stress, which activate RIPK3 via Z-DNA-binding protein 1 (ZBP1)." (PMID 40221399, 2025). "While this pathway is also critical for other death factors, such as FasL or TRAIL, -induced necroptosis, RIPK1 is not involved in viral infection and Toll-like receptor (TLR)-mediated necroptosis, although RIPK3 and MLKL seem to be the common players of necroptosis." (PMID 33976222, 2021).
colitis (42 papers, 2016 to 2025). Inflammation of the colon. "The deficiency of RIPK3 in mice cells was connected with the inhibition of colitis-associated tumorogenesis." (PMID 41303584, 2025). "The analysis showed that RIPK3 is upregulated in mouse colitis-associated cancer cells and in human colon cancer cells." (PMID 41303584, 2025). "This process is often accompanied by the inhibition of Trim11-mediated autophagy-dependent degradation of RIPK3, which promotes the necroptosis of IECs and aggravates colitis, leading to the progression of inflammation-associated CRC." (PMID 38684668, 2024). "challenged these results in their report showing that germline deficiency of MLKL or RIPK3 exacerbates the severity of DSS-induced colitis." (PMID 37409125, 2023). "Consistently, administration of RIPK3 inhibitor showed significant alleviation of colitis in Gab1-deficient mice." (PMID 36795486, 2023). "Deletion of Gab1 in epithelial cells rendered mice susceptible to dextran sodium sulfate–induced (DSS-induced) colitis by perpetuating RIPK3-dependent necroptosis." (PMID 36795486, 2023). "In contrast to our initial expectations, ADAM17ex/ex/RIPK3−/− mice showed the same increased susceptibility as ADAM17ex/ex mice in acute or chronic models of DSS-induced colitis." (PMID 29560122, 2018). "RIPK3-deficient mice were highly susceptible to colitis-associated CRC and exhibited greater production of pro-inflammatory mediators and tumor promoting factors." (PMID 27344176, 2016). "Collectively, these data indicate that RIPK3-deficiency contributes to increased tumor development and progression in the colon and imply that RIPK3 has an important protective function during colitis-associated CRC." (PMID 27344176, 2016). "We demonstrate that Ripk3−/− mice were highly susceptible to colitis-associated CRC and showed greater production of pro-inflammatory and tumor promoting factors." (PMID 27344176, 2016). "Together, these findings uncover RIPK3 as a critical tumor suppressor during intestinal inflammation and colitis-associated CRC." (PMID 27344176, 2016). "GSK’872, a chemical inhibitor of RIPK3 kinase activity, was evaluated in DJ-1-deficient colitis." (PMID 40877233, 2025). "Moreover, in vivo, we found that inhibition of RIPK3 or MLKL pharmacologically completely rescued DJ-1 deficiency-related colitis." (PMID 40877233, 2025). "Another in vitro study was focused on role of RIPK3 in colitis-associated tumorogenesis." (PMID 41303584, 2025). "Moreover, HSD was shown to significantly promot the IBD process in vivo and mice with genetic deletion of RIPK3/MLKL was susceptible to DSS-induced colitis." (PMID 37691056, 2023). "Genetic deletion of RIPK3 or MLKL was susceptible to DSS-induced colitis in vivo." (PMID 37691056, 2023). "We next evaluated whether the failure of Casp8–/–Ripk3–/– mice to resolve an intestinal C. rodentium infection was associated with altered colitis severity at 14 dpi." (PMID 37080966, 2023). "RIPK3 inhibition alleviates colitis in epithelial Gab1-deficient mice." (PMID 36795486, 2023). "Moreover, RIPK3 knockout mice have a higher risk of developing colitis-associated CRC by producing an increased amount of pro-inflammatory or tumor-promoting factors, such as the transcription factor STAT3." (PMID 33050394, 2020). "Ripk3−/− mice have been recently shown to be highly susceptible to DSS-induced colitis." (PMID 27344176, 2016). "Notably, Ripk3−/− mice were highly susceptible to colitis when compared to WT mice, as 35% of these mice died and exhibited dramatic body weight loss after only one cycle of DSS treatment." (PMID 27344176, 2016). "Having displayed the involvement of RIPK3 in colitis-associated CRC in mice, we sought to determine whether the expression of RIPK3 was reduced in IBD-related CRC." (PMID 27344176, 2016).